OBP2A (odorant binding protein 2A)
Description:
Binds and transports small hydrophobic volatile molecules with a higher affinity for aldehydes and large fatty acids, including undecanal, palmitic acid, efficient aldehydes, benzenic aldehydes, heterocyclic aldehydes and aliphatic acids.
Synonyms: OBPIIa; hOBPIIa; OBP; LCN13; OBP2C
Tractability: Antibody: UniProt places it where antibodies can reach, with high confidence; UniProt predicts a signal peptide or a membrane-spanning region; its Gene Ontology location is reachable by antibodies, with medium confidence.
Gene: Protein-coding gene on chromosome 9 (135,545,504 to 135,549,969, forward strand). Ensembl gene ENSG00000122136.
Subcellular location: Secreted
Gene Ontology:
Molecular function: odorant binding; small molecule binding
Biological process: glucose homeostasis; sensory perception of chemical stimulus
Cellular component: extracellular region
Genetic constraint (gnomAD): Loss-of-function variants: 12 observed, 17.99 expected, observed/expected ratio (o/e) 0.67, 90% interval 0.43 to 1.08. The upper end of that interval is the gene's LOEUF score, 1.08, which puts it in group 4 of 6, group 1 being the genes least tolerant of losing a copy. Missense variants: 189 observed, 207.39 expected, observed/expected ratio (o/e) 0.91, 90% interval 0.81 to 1.03. Synonymous variants: 86 observed, 83.86 expected, observed/expected ratio (o/e) 1.03, 90% interval 0.86 to 1.23.
Homologues: Orthologues: chimpanzee OBP2B (76% identical), mouse Obp2b (46% identical), rat Obp2b (45% identical), mouse Obp2a (39% identical), rat Lcn4l2 (38% identical), rat Obp2a (37% identical), rat Lcn4 (36% identical), mouse Lcn4 (35% identical), rat Obp2bl1 (34% identical), rat AABR07051244.1 (24% identical). Paralogues in human: OBP2B (90% identical), LCN1 (45% identical), LCN15 (24% identical), PTGDS (22% identical), PAEP (21% identical), LCN10 (20% identical), LCN6 (19% identical), LCN2 (18% identical), LCN12 (18% identical), LCN9 (18% identical), LCNL1 (15% identical), LCN8 (12% identical).
Diseases named in the same sentence as OBP2A in open-access papers:
OBP2A is named in the same sentence as 13 diseases in open-access papers, as found by Europe PMC text mining. Sharing a sentence is not in itself a finding about the gene and the disease. The quoted sentences say what the papers report.
atopic dermatitis (1 paper, 2024). "Consistent with the results of lipidomics and transcriptome analysis in OBP2A-knockdown 3DE-model, we observed a reduction of OBP2A expression and an abnormal free fatty acid distribution in atopic dermatitis lesional skin." (PMID 39502293, 2024). "Significant increases in free fatty acids (FA 14:1, FA 16:0, FA 16:1, FA 18:1, FA 20:1, FA 22:0) and short C34 ceramide NS, which have been reported to be increased in atopic dermatitis skin, were observed in the OBP2A-knockdown 3DE-model." (PMID 39502293, 2024). "OBP2A expression was markedly decreased in the epidermis of atopic dermatitis lesional skin." (PMID 39502293, 2024). "To get insight into the mechanism of the decline in OBP2A expression in atopic dermatitis lesional skin, we measured changes in OBP2A expression in human keratinocytes treated with type 2 cytokine IL-4 or IL-13, known to be involved in the pathogenesis of atopic dermatitis." (PMID 39502293, 2024). "Therefore, we next examined OBP2A expression in atopic dermatitis lesional skin samples, and found that it was markedly decreased compared with that in healthy skin." (PMID 39502293, 2024). "Finally, atopic dermatitis is influenced by many factors and mechanisms, so it will be necessary to investigate a larger number of samples of atopic dermatitis lesional skin to confirm the role of OBP2A in atopic dermatitis." (PMID 39502293, 2024). "Consistent with our data obtained in the OBP2A-knockdown 3DE-model, ToF-SIMS imaging data also showed a distribution of free fatty acid in the upper layer of healthy skin, whereas irregularly distribution of free fatty acid was observed in atopic dermatitis skin." (PMID 39502293, 2024).
lipid metabolism disorders (1 paper, 2024). "Therefore, to investigate whether cellular lipid metabolism disorders could cause the impairment of epidermal barrier formation in the OBP2A-knockdown 3DE-model, we performed lipidomics analysis using LC-MS/MS." (PMID 39502293, 2024).
cancer (2 papers, 2021 to 2024). A tumor composed of atypical neoplastic, often pleomorphic cells that invade other tissues. "Although STAP1 and OBP2A remain inadequately investigation in TME or cancer related research, our results might provide some clues for further studies." (PMID 33552736, 2021).
tumour (1 paper, 2024). "Further multivariate analysis unveiled significant insights: LRP1, PAEP, PI3, OBP2A, and IL27RA genes exhibited higher levels in the tumour group, whereas FOS, PDGFRA, and FGF7 showed higher expression in normal ovarian tissue (all p < 0.001)." (PMID 39063239, 2024). "LRP1, AKT2, PI3, IL27RA, OBP2A, and PAEP were found to be more expressed in OC tumour samples than in normal tissues." (PMID 39063239, 2024).
OBP2A also shares sentences with these, for which no sentence is quoted: Obesity (3 papers); diabetes (2); Insulin resistance (2); Glucose intolerance (1); Hepatic steatosis (1); hyperglycaemia (1); inflammatory bowel disease (1); liver disease (1); metabolic disorders (1).